FGF21 (fibroblast growth factor 21)
Diseases named in the same sentence as FGF21 in open-access papers (continued):
Sharing a sentence is not in itself a finding about the gene and the disease.
Obesity (continued). "The endocrine factor fibroblast growth factor 21 (FGF21) is being explored as a potential treatment for obesity and diabetes as it enhances insulin sensitivity and decreases triglyceride levels." (PMID 27528232, 2016). "Since FGF21 has been shown to be a key regulator of obesity, the enhancement of FGF21 expression has therapeutic potential." (PMID 27057099, 2016). "Our data demonstrated that compared with obese patients, FGF21 levels were positively correlated with obesity-related AN and markers of insulin resistance (fasting insulin, HOMA-IR)." (PMID 27190511, 2016). "Although at the protein level, FGF21 was slightly increased in animals with diet induced obesity, a similar reduction in protein was observed with fasting (DIO fed 1 ± 0.23; DIO fasted 0.08 ± 0.07; p = 0.003)." (PMID 26872145, 2016). "Previous research has suggested that FGF21 is a potential therapeutic effect for the treatment of human diabetes and obesity." (PMID 27057099, 2016). "Other families of FGF such as FGF21 have higher levels in obesity, type 2 diabetes and metabolic syndrome." (PMID 27471744, 2016). "Genetic overexpression FGF21 or pharmacological treatment of FGF21 can correct glucose and lipid metabolism and has beneficial effects in mouse models of obesity." (PMID 27409675, 2016). "Fibroblast growth factor 21 (FGF21) is a master metabolic regulator that has a striking ability to reverse obesity, diabetes, and injury as well as prolong life span." (PMID 26701854, 2016). "Muscle-specific ATF7 knockout mouse also showed resistance against diet-induced obesity and insulin resistance owing to FGF21 induction." (PMID 28025491, 2016). "Previous studies have shown that administration of Fgf21 can lower triglyceride levels in genetic models of obesity, can reduce ceramide levels in obese animals and attenuate hyperglycemia in diabetic mice." (PMID 27583452, 2016). "For example, transgenic mice that overexpress Fgf21 and mice administered FGF21 resist diet-induced obesity." (PMID 26487695, 2016). "Administration of FGF21 to rodents with diet-induced or genetic obesity and diabetes resulted in potent antihyperglycemic and triglyceride lowering effects." (PMID 26701854, 2016). "FGF21 has numerous insulin-like effects and serves as a potential therapeutic target for diabetes and obesity." (PMID 27190511, 2016). "Despite the up-regulation of FGF21 expression, treatment with recombinant FGF21 attenuates obesity- and diabetes-induced glucose and lipid dysregulation." (PMID 27498701, 2016). "Experiments with HFD-fed β-klothoCamk2a mice showed that β-klotho in the hypothalamus is needed to recapitulate the majority of the beneficial effects of FGF21 treatment during obesity." (PMID 26834701, 2015). "The correlation of FGF21 with browning has been suggested as the mechanism by which FGF21 improves metabolic disorders, such as obesity and type 2 diabetes." (PMID 26441837, 2015). "In animal models, obesity and T2DM have decreased serum FGF-21 levels and reduced FGF-21 gene expression and, therefore, proposed that obesity is an FGF21-resistant state." (PMID 26497746, 2015). "This phenomenon of reduced FGF21 action in obesity has been attributed to an abnormal reduction in the expression of the FGF21 co-receptor, β-Klotho, in white adipose tissue, commonly observed in rodent models of obesity and in obese individuals." (PMID 26379627, 2015). "A recently published report has provided novel insight into FGF21-induced cardiac effects in obesity and ischemia." (PMID 26161641, 2015). "Actually in human study, circulating FGF21 levels are elevated in obesity, type 2 diabetes and dyslipidemia." (PMID 25850006, 2015). "FGF21 expression is induced under different disease conditions, such as type 2 diabetes, obesity, chronic kidney diseases, and cardiovascular diseases, and it has a broad spectrum of functions in regulating various metabolic parameters." (PMID 26594197, 2015).
Obesity (continued). "And mice with over-expression of FGF21 were protected from diet-induced obesity, while FGF21 knockout mice developed mild obesity and impaired glucose homeostasis as these mice became aged." (PMID 25850006, 2015). "For example, Samson SL and colleagues found that combined treatment with pioglitazone and exenatide decreased circulation FGF21 levels, hepatic FGF21 protein and mRNA, and hepatic fat in a mouse model of obesity and in obese patients with T2DM." (PMID 26226139, 2015). "FGF21 is considered a typical fasting hormone and although seemingly paradoxical, circulating FGF21 levels are also elevated during obesity." (PMID 26834701, 2015). "FGF1, FGF15/19, FGF21, and their targets provide interesting therapeutic possibilities for the treatment of metabolic diseases, such as obesity, non-alcoholic fatty liver disease, type 2 diabetes, and atherosclerosis." (PMID 26834701, 2015). "Similar to bispecific Avimers, these bispecific antibodies also display activities similar to FGF21, stimulate thermogenic activity in BAT, induce WAT browning, and ameliorate obesity, insulin resistance, and associated metabolic defects." (PMID 26594197, 2015). "In a rat model, cardiac FGF21 was expressed and secreted in an autocrine-paracrine manner in response to obesity and hypoxia, and ischemia upregulated this FGF21 expression and secretion." (PMID 26091256, 2015). "During the past decade, FGF-21 has been shown to be a novel regulator of metabolism and a potential therapeutic target for the treatment of obesity and diabetes." (PMID 26441838, 2015). "Most data on FGF21 signaling in WAT come from experiments in which FGF21 is pharmacologically administered or overexpressed in obese rodents, revealing potent effects on the amelioration of the metabolic profile during obesity." (PMID 26834701, 2015). "FGF21 also exerts anti-obesity effects through regulation of energy expenditure in BAT by stimulating sympathetic nerve activity through a mechanism that depends on the neuropeptide corticotrophin-releasing factor (CRF)." (PMID 26441837, 2015). "Recently, fibroblast growth factor-21 (FGF21) has been related to insulin resistance, type 2 diabetes mellitus, obesity and the metabolic syndrome." (PMID 25592553, 2015). "The recently discovered metabolic regulator fibroblast growth factor 21 (FGF21) has been shown to exert profound antidiabetic and triglyceride-lowering effects in rodent models of diabetes and obesity, as well as in diabetic rhesus monkeys." (PMID 26089880, 2015). "Our data provides novel insights into the cardio-protective effects of FGF21 within the context of obesity related CVD." (PMID 24498293, 2014). "An autophagy deficiency and subsequent mitochondrial dysfunction increased the production of FGF21 as a myokine to promote protection against diet-induced obesity and insulin resistance." (PMID 25071723, 2014). "Myocytic FGF21 protects against diet-induced obesity and insulin resistance, induces the browning of WAT, and protects against cardiac hypertrophy." (PMID 25071723, 2014). "More importantly, this cardio-protective response induced by FGF21 was reduced in obesity, although the cardiac expression profiles and circulating FGF21 levels were increased." (PMID 24498293, 2014). "Due to the beneficial effects of FGF21 in experimental models, FGF21 is regarded as a potentially promising therapeutic agent for the treatment of metabolic disorders such as obesity and diabetes." (PMID 25365322, 2014). "The induction of Fgf21, resistance to diet-induced obesity, and amelioration of insulin resistance were also observed in the livers of mice with autophagy deficiencies." (PMID 25071723, 2014). "FGF21 resistance had been found in obesity and in cardiovascular failure, leading to compensatory upregulation of adiponectin." (PMID 24895642, 2014).
Obesity (continued). "Similar findings were demonstrated in the case of Akt [P<0.05; Figure 5C3] and AMPK phosphorylation states [P<0.05; Figure 5C4], further supporting decreased FGF21 signalling in cardiac tissue in obesity." (PMID 24498293, 2014). "Our novel data also shows the functionally significant differences in cardiac secreted FGF21 in obesity involving βKlotho." (PMID 24498293, 2014). "Collectively, our findings provide novel insights into FGF21-induced cardiac effects in obesity and ischemia." (PMID 24498293, 2014). "The effects of FGF21 on the attenuation of obesity-induced impairments in insulin signaling in the liver and skeletal muscle were also impaired in adiponectin knockout mice." (PMID 25071723, 2014). "Cardiac FGF21 was expressed and secreted (real time RT-PCR/western blot and ELISA) in an autocrine-paracrine manner, in response to obesity and hypoxia, involving FGFR1-βKlotho components." (PMID 24498293, 2014). "Studies in mice and humans demonstrated that Fgf21 had the potential of preventing diet-induced obesity and metabolic disorders in obese cases." (PMID 24587261, 2014). "In an ex vivo Langendorff system, we show that FGF21 induced cardiac protection and restoration of cardiac function involving autocrine-paracrine pathways, with reduced effect in obesity." (PMID 24498293, 2014). "Here we attempt to unify these developments with beneficial pharmacological effects of FGF21 on obesity in respect to inter-organ stress communication and mechanisms." (PMID 24385972, 2013). "In humans, serum FGF21 levels are paradoxically increased in metabolic diseases such as obesity, diabetes, and CVD (60, –62), which infer FGF21 resistance in humans." (PMID 23970879, 2013). "There is increasing evidence to suggest the utility of FGF21 as a therapeutic for treating diabetes and obesity." (PMID 23630589, 2013). "The endocrine hormone FGF21 has attracted considerable interest as a potential therapeutic for treating diabetes and obesity." (PMID 23630589, 2013). "FGF21 is a novel secreted protein with robust anti-diabetic, anti-obesity, and anti-atherogenic activities in preclinical species." (PMID 24039848, 2013). "We showed previously that FGF21 is induced in the liver by diverse transcriptional regulators in response to a wide range of stress conditions that include obesity, fatty liver disease and carcinogenesis." (PMID 24279986, 2013). "Serum levels of FGF-21, which has been suggested as a potential candidate for the treatment of diabetes, are increased in obesity." (PMID 24078096, 2013). "Emerging metabolic regulators such as fibroblast growth factor 21 (FGF21), other FGFs and myonectin appear to play roles in obesity and insulin resistance, from our experience." (PMID 23970879, 2013). "Fibroblast growth factor 21 is a novel hormonal regulator with the potential to treat a broad variety of metabolic abnormalities, such as type 2 diabetes, obesity, hepatic steatosis, and cardiovascular disease." (PMID 23536797, 2013). "Over-expression or treatment with recombinant FGF21 protects mice from development of obesity and fatty liver and improves insulin sensitivity and comparable metabolic benefits are also observed in rhesus monkeys." (PMID 24205333, 2013). "Do the roles of FGF21 in the stress response and treatment of obesity occur through the same mechanisms?" (PMID 24385972, 2013). "Mounting evidence from animal-based studies suggests FGF-21 as a potent metabolic regulator with multiple beneficial effects on obesity and diabetes." (PMID 24078096, 2013). "In murine models, chronic administration of FGF-21 increases insulin-mediated glucose uptake in muscle, but only in diet induced obesity." (PMID 23533568, 2013). "Both LY2405319 and FGF21 were subsequently shown to exert nearly identical pharmacologic effects when administered to two distinct mouse models of obesity and Type 2 diabetes." (PMID 23536797, 2013).
Obesity (continued). "Enhanced serum FGF21 level has been previously demonstrated in subjects with obesity, diabetes, and dyslipidemia." (PMID 23981342, 2013). "FGF21 is also postulated to be a metabolically protective cytokine since treatment with FGF21 mimetics protects against obesity, fatty liver and insulin resistance in mouse and primates." (PMID 24205333, 2013). "FGF21 has been highlighted as a new drug candidate for enhancing insulin sensitivity, inducing lipolysis, and preventing diet-induced obesity in many in vitro and in vivo studies (56, –58)." (PMID 23970879, 2013). "Circulating Fibroblast Growth Factor 21 (FGF21) levels are increased in insulin resistant states such as obesity, type 2 diabetes mellitus and gestational diabetes mellitus (GDM)." (PMID 23755203, 2013). "FGF21 is a promising intervention therapy for metabolic diseases as fatty liver, obesity and diabetes." (PMID 23590285, 2013). "In genetic models of obesity such as the ob/ob mouse either direct treatment with FGF21 or its induction via feeding of a high fat very low carbohydrate diet leads to weight loss and metabolic improvement." (PMID 22675463, 2012). "It is reported that FGF21 is induced preferentially in the liver under the control of PPARα in response to fasting, ketogenic diet and in type 2 diabetes and obesity." (PMID 22442730, 2012). "In clinical studies, a positive correlation between FGF21 plasma levels and many parameters of obesity (e.g. body mass index (BMI), waist circumference, waist to hip ratio and fat percentage) has been shown)." (PMID 22701542, 2012). "This interpretation is in agreement with the increased FGF21 levels reported in patients with the metabolic syndrome, obesity, and impaired glucose tolerance." (PMID 22701542, 2012). "In contrast, FGF21 is induced in the liver in response to liver perturbation and during metabolic extremes that include those induced by starvation and obesity." (PMID 23106963, 2012). "Treatment with FGF21 corrects metabolic disorders such as hyperglycemia, hyperlipidemia and insulin resistance in rodent and primate models of diabetes and obesity." (PMID 22442730, 2012). "Both FGF19 and FGF21 transgenic mice are resistant to diet-induced obesity, have decreased adiposity and improved insulin sensitivity, glucose disposal, and plasma lipid profiles." (PMID 22457778, 2012). "Our group and others have previously reported on the efficacy of FGF21 in the treatment of obesity in animal models." (PMID 22675463, 2012). "Consistent with the established anti-obesity action of FGF21, WT animals exhibited sustained weight loss of approximately 9 g which was significantly attenuated in the KLBKO mice." (PMID 23209629, 2012). "Several studies have now demonstrated that administration of FGF19 or FGF21 can have beneficial effects in rodent and primate models of obesity and diabetes." (PMID 22675463, 2012). "For example, FGF21 activates glucose uptake in adipocytes and protectes animals from diet-induced obesity." (PMID 21949781, 2011). "Serum FGF21 levels are increased in patients with type 2 diabetes, gestational diabetes, and obesity, indicating FGF21 to be a potential new marker in patients with type 2 diabetes." (PMID 21331285, 2011). "Diet-induced obese mice also have increased serum (endogenous) FGF21 levels and respond poorly to exogenous FGF21, indicating that obesity is an FGF21-resistant state." (PMID 21331285, 2011). "FGF-21 knockout (FGF-21KO) mice developed mild obesity and impaired glucose homeostasis, as these mice aged." (PMID 22046277, 2011). "Furthermore, FGF21 treatment ameliorated hyperglycemia, dyslipidemia, and obesity in diabetic monkey models." (PMID 39764565, 2025). "The upregulated expression and secretion of FGF21 may imply that obesity could be a condition resistant to FGF21." (PMID 41373582, 2025).
Obesity (continued). "A recent study investigating the effects of β-Klotho protein gene ablation in mice led to a decrease in energy expenditure, without concomitant disruption of energy intake, resulting in a positive energy balance increasing the likelihood of developing obesity due to reduction of FGF21." (PMID 40064726, 2025). "Moreover, the transcription factor Sp1 has been identified as a positive regulator of FGF21, particularly in response to obesity and liver carcinogenesis." (PMID 40806358, 2025). "Recently, the beneficial effects of FGF21, which counteracts obesity and its related metabolic diseases by maintaining whole-body energy balance and protecting the liver from excessive triglycerides production and storage, have attracted considerable attention." (PMID 40756666, 2025). "Furthermore, due to their role in regulating dietary preference, impaired signalling through FGF21 and OXT underlies dietary choices that exacerbate obesity and linked diseases." (PMID 40225784, 2025). "Although FGF21 has biological functions similar to adiponectin, it has been shown that individuals with obesity may develop resistance to its actions." (PMID 40149850, 2025). "FGF21, a class of hepatokines that regulate lipid and glucose metabolism, has garnered much attention due to its translational potential for the management of obesity-related metabolic comorbidities." (PMID 40006605, 2025). "Prolonged BF protects from obesity by the hypothalamic action of hepatic FGF21." (PMID 40429638, 2025). "This discrepancy led to the concept of an “FGF21-resistant state ” in obesity." (PMID 41516073, 2025). "Gdf15 and Fgf21 expression are regulated by similar underpinning molecular mechanisms, and circulating levels frequently increase in tandem during the development of obesity." (PMID 40787810, 2025). "Despite the positive effects of FGF-21 on metabolism, up-regulation of FGF-21 and its correlation with BMI has been reported in obesity, leading to the suggestion FGF-21 resistance condition may occur in obesity." (PMID 41341131, 2025). "While FGF21 has been considered a stress hormone that helps the body cope with nutrient restriction, both circulating and tissue levels of this hormone are elevated in obesity, suggesting the presence of FGF21 resistance as an adaptive response." (PMID 40906363, 2025). "Considering its short half-life, endogenous FGF21 is not suitable for clinical application; therefore, long-acting FGF21 analogs have been used in preclinical trials for the treatment of obesity and associated metabolic disorders." (PMID 40756666, 2025). "GDF15 levels increase significantly in patients with obesity and normoglycemia and in those with obesity and impaired glucose tolerance or type 2 diabetes, while FGF21 concentrations significantly decrease in patients with obesity and impaired glucose tolerance or type 2 diabetes." (PMID 40377893, 2025). "FGF21 counteracts muscle stress, involves in protecting against diet‐induced obesity and IR." (PMID 39764565, 2025). "Additionally, another study investigates the potential of fibroblast growth factor 21 (FGF21) gene therapy using AAV vectors to counteract obesity, insulin resistance, and T2D." (PMID 40568561, 2025). "For example, in individuals with obesity and type 2 diabetes, FGF21 analogs attenuate dyslipidemia but have less impact on glycemic control, which demonstrates the differences that still exist among different FGF21 analogs and the differences in action between species." (PMID 40881124, 2025). "However, DR-10,624, a GLP-1/GCG/fibroblast growth factor 21 (FGF-21) triple agonist is under investigation for individuals with severe hypertriglyceridemia (not limited to individuals with obesity; NCT06555640)." (PMID 40741227, 2025). "Thus, FGF21 has significant potential as a therapeutic agent for the treatment of diabetes and obesity." (PMID 39884432, 2025).